IL2 (interleukin 2)
Diseases named in the same sentence as IL2 in open-access papers (continued):
Sharing a sentence is not in itself a finding about the gene and the disease.
melanoma (continued). "However, in 1993, results from a randomized trial of 181 patients with advanced melanoma or renal cancer comparing treatment with IL-2 alone or in conjunction with LAK cells showed that the observed anti-tumor effects tended to be due to IL-2 alone, thereby hampering clinical studies of LAK cells." (PMID 35720306, 2022). "Therefore, the prognosis of melanoma might be improved by increasing IL-2 levels by relieving depression and increasing QOL through psychological support." (PMID 36405903, 2022). "Indeed, treatment with IL-2 was the first immunotherapy approach used in advanced melanoma." (PMID 35361879, 2022). "Additionally, the intratumoral injection of GD2 or epithelial cell adhesion molecule (EpCAM)-targeting IL-2 immunocytokines increased the anti-tumor effect and immune cell presence in neuroblastoma and melanoma in vivo compared to intravenous administration and unconjugated IL-2." (PMID 33803078, 2021). "In addition, a randomized phase II study evaluating sequential therapy with aflibercept and high-dose IL-2 versus high-dose IL-2 alone for inoperable stage III or IV melanoma, demonstrated superior antitumor efficacy with combination therapy compared to monotherapy." (PMID 33964953, 2021). "Of note, we also observed that although not affected by PD-1/PD-L1 signaling, the KO6 T cell clone globally produced lower levels of IFN-γ and IL-2 than the WT4 T cell clone especially in response to melanoma cell lines, that could be a disadvantage for subsequent in vivo experiments." (PMID 32001504, 2020). "In addition, intratumoral administration of ipilimumab in combination with interleukin-2 (IL-2) was investigated in a phase I trial in patients with unresectable stage III/IV melanoma, where a local response of injected lesions was observed in 67% patients, and an abscopal response in 89%." (PMID 33182610, 2020). "Indeed, when intralesional IL2 was given with systemic ipilimumab, severe irAEs were present and there were no objective responses to report, underpinning the importance of further investigation into intralesional delivery in advanced melanoma." (PMID 32455916, 2020). "Our findings suggest that the advantage of combinatorial ACT may result from the induction of stronger infiltration of endogenous CD8+ T cells into tumor, stronger systemic CD8+ T cell responsiveness to tumor antigen, temporal differences in melanoma cell killing, and paracrine IL-2 effects." (PMID 29843822, 2018). "NFAT proteins were first discovered in T cells in the 1980s, as transcriptional activators of interleukin-2 (IL2), a key regulator of T cell immune response, that at the time was also successfully introduced into practice as immune therapy for some renal cancers and malignant melanoma." (PMID 29464052, 2018). "However, identification of predictive biomarkers and/or established efficacy in a PD-1 refractory cohort may result in HD IL-2 remaining in the melanoma therapeutic armamentarium." (PMID 28923120, 2017). "Therefore, targeting the immune system in melanoma patient with IL-2 and IFN-α could be important therapeutic approach." (PMID 28137308, 2017). "In the B16 melanoma system, we have now demonstrated in mammary carcinoma that culturing B/I-activated lymphocytes from tumor-sensitized mice in IL-7/15/21 results in a much higher yield of viable cells than those grown in IL-2, IL-21, IL-2/21 and even IL-7/15." (PMID 28146052, 2017). "In addition to its therapeutic applications, IL-2 became a key cytokine used in the ex vivo expansion of T cells isolated from tumors, and applied in the transfer of highly expanded tumor infiltrating lymphocytes (TILs) for melanoma." (PMID 28927416, 2017). "However, further study is warranted to analyse whether the defects of STAT1 signaling are observed in HD IL-2 treated melanoma patients who progressed from disease in comparison to patients who responded to IL-2 therapy." (PMID 27153543, 2016).
melanoma (continued). "Although our previous data showed no defect in the proliferation capacity and pSTAT5 activation of different lymphocyte subsets from melanoma patients compared to healthy controls, there could be impairment in other IL-2-induced effector functions, such as inflammatory cytokine production." (PMID 27153543, 2016). "Previous studies have suggested that melanoma patients had multiple defects in their immune systems induced by tumor cells that may facilitate resistance to immunotherapy, such as with HD IL-2." (PMID 27153543, 2016). "Thus, an insufficient secretion of IFN-γ by PBMC from melanoma patient in response to HD IL-2 treatment could lead to defective pSTAT1 activation." (PMID 27153543, 2016). "IL-2 and GM-CSF can not only stimulate the proliferation and cytotoxicity of TILs in the presence of tumor cells but also promote the activation and cytotoxicity of monocytes to attack melanoma in vitro and prolong the survival of polymorphonuclear neutrophils." (PMID 26850448, 2016). "Melanoma and colorectal tumor associated fibroblasts could inhibit NK cell activity through cell–cell contact in vitro and through secretion of PGE2 or IDO that abrogated IL-2 induced NKp44, DNAM-1, and NKp30 upregulation." (PMID 25972872, 2015). "This retrospective study confirms that IL-2 can be administered safely in the community setting, that severe toxicities can be managed with a well-trained biotherapy team and that excellent clinical results with durable responses can be achieved in melanoma and RCC." (PMID 24855563, 2014). "His melanoma was initially treated with high-dose interleukin-2 (IL-2) in May 2011." (PMID 25317333, 2014). "Interleukin-2 (IL-2), a cytokine signaling molecule necessary for growth, proliferation and differentiation of T-lymphocytes, has demonstrated antitumor activity in renal cell cancer and melanoma; previous studies on patients with NSCLC treated with IL-2 reported relatively long survival." (PMID 25271833, 2014). "Also, the T cell stimulant IL-2 is currently used to treat metastatic renal cancer and melanoma." (PMID 23577028, 2013). "Moreover, IL-2 has been approved for clinical use in patients with metastatic renal cell carcinoma and melanoma and has been tested with adoptively transferred immune cells for treating patients with melanoma." (PMID 24391824, 2013). "Research conducted by the Cytokine Working Group and others have included studies on the use of IL-2, both as a single agent or in combination with other cytokines or chemotherapy, in the treatment of solid tumors and have shown benefits for patients with melanoma or renal cell cancer." (PMID 21281484, 2011). "To evaluate whether TILs with specific tumor reactivity are maintained in aAPC expanded cultures, we selected TILs isolated and expanded in IL-2 from melanoma fragments, where tumor antigen-specific T cells are frequently detected for expansion with KT64/BBL aAPCs." (PMID 21827675, 2011). "Moreover, we showed that intratumoral injection of an IL-2-expressing Ad vector could induce tumor regression in patients with advanced melanoma." (PMID 20670430, 2010). "Thus, treatment with IL-21 + low-dose IL-2 after the adoptive transfer of pmel Tg CD8+ T cells into mice with established B16 melanoma tumors (pmel Tg/B16 model) might yield anti-tumor effects comparable to or greater than those observed with IL-21+IL-15." (PMID 16772043, 2006). "The reproducible observation that virtually all malignant cells can be lysed by IL-2 stimulated lymphocytes in a manner directly related to the intensity of IL-2 administration encouraged the pursuit of aggressive, intensive clinical trials, especially in renal cell carcinoma and melanoma." (PMID 15329148, 2004). "However, toxicity was increased in melanoma patients treated with IL-2." (PMID 11308250, 2001).
melanoma (continued). "Intravenous aNP-mRNAIL-2 administration in mice led to sustained IL-2 production in the spleen and lymph nodes, significantly inhibiting tumor growth in B16F10 melanoma and MC38 colon cancer models." (PMID 41928788, 2026). "Celastrol (CEL), an IL-2/CD25 binding inhibitor, impacts melanoma treatment by blocking IL-2 from interacting with the CD25 receptor, thereby disrupting IL-2 signaling in T cells." (PMID 40636453, 2025). "CEL's ability to inhibit IL-2/CD25 binding and its synergistic effect with other treatments highlight its potential for use in combination therapies for melanoma." (PMID 40636453, 2025). "In adoptive T-cell therapy (ACT) for melanoma, combining total body irradiation (TBI) and IL-2 aims to improve the persistence and function of transferred tumor-specific T cells." (PMID 40636453, 2025). "CD8+ T cells were isolated from the peripheral blood mononuclear cells (PBMCs) of 16 melanoma patients and activated with CD3/CD28/IL-2 stimulation, with CD45+/CD3+/CD8+ cells identified as the CD8+ T-cell population." (PMID 40860143, 2025). "Before the disruption in the clinic of immune checkpoint inhibitors (ICI), early immunotherapy efforts focused on harnessing the immune system using cytokines, such as interleukin-2 (IL-2) and interferon-alfa (IFN-α) in patients with melanoma and renal cancer." (PMID 40508202, 2025). "IL-2, approved by the FDA in 1998, is a commonly used cytokine serving as adjuvant treatment for patients with melanoma." (PMID 40574005, 2025). "Amongst the first forms of immunotherapy for melanoma were interferon-alpha (IFN) and high doses of interleukin-2 (IL-2)." (PMID 40004731, 2025). "Dacarbazine (1975), high-dose interleukin-2 (1992), and high-dose interferon α-2b (1995) were approved by the U.S. Food and Drug Administration (FDA) for the treatment of advanced melanoma." (PMID 40932870, 2025). "In melanoma, the chimeric protein soluble extracellular domain of TGF-βR II (FIST), which merges IL-2 with the soluble extracellular domain of TGF-β receptor II, functions as a decoy receptor for TGF-β." (PMID 40636453, 2025). "The results demonstrated that, in the activated state, CM from Vin-treated melanoma cells similarly enhanced the expression of IFNγ, GZMB, IL-2, and TNFα in Jurkat cells." (PMID 40866941, 2025). "An immunocytokine based on the L19 antibody fused to IL-2 (L19-IL2), in combination with L19-TNF, has recently met the primary endpoint in a Phase III trial in melanoma [NCT03567889]." (PMID 39773310, 2025). "The variable IL-2 kinetics, elevated in some NSCLC cases at baseline but sustained in melanoma, likely reflect differing T-cell functional states." (PMID 41020868, 2025). "Despite a limited number of patients, this study provides preliminary insight into the potential predictive role of serum cytokines, TNF-α, IL-2 and IL-10 in patients diagnosed with NSCLC and melanoma undergoing anti-PD-1 immunotherapy with Nivolumab." (PMID 41020868, 2025). "IL2 was the first cytokine in human history used for cancer treatment and it has been approved by the FDA as a monotherapy for renal cell carcinoma and melanoma and was found to mediate tumor regression in human cancer patients." (PMID 41050655, 2025). "For example, IL-2, the first FDA-approved cytokine for advanced melanoma and renal cell carcinoma, supports T-cell survival and expansion." (PMID 40866941, 2025). "Novel combinations are also arising, including the anti-PD-1/interleukin-2 (IL-2) bsAb fusion protein, IBI363, that achieves simultaneous PD-1 blockade and IL-2 delivery for melanoma treatment." (PMID 41250091, 2025). "Although IL-2 monotherapy showed early promise in metastatic renal cell carcinoma (RCC) and melanoma, its clinical utility was limited by toxicity and Treg activation, prompting a shift toward combination regimens." (PMID 41268548, 2025).
melanoma (continued). "Circulating cytokines and especially IL-17α, IL-2, and TGF-β have high predictive value on immune-related toxicities in melanoma patients receiving anti-PD-1 therapies." (PMID 38520533, 2025). "Follow-up samples indicated that after the removal of malignant melanoma, the serum levels of GM-CSF, IFN-γ, MCP-1, IL-18, and IL-2 increased significantly." (PMID 40711287, 2025). "This study seeks to address these gaps by providing real-world longitudinal data on serum TNF-α, IL-2, and IL-10 dynamics in a cohort of patients with stage IV NSCLC and melanoma undergoing anti-PD-1 therapy with Nivolumab." (PMID 41020868, 2025). "Other cytokine trajectories, including IL-2 and TNF-α patterns, showed variability across cancer types and timepoints, but given the limited sample size, particularly in melanoma, these results remain exploratory." (PMID 41020868, 2025). "Preclinical and clinical studies have demonstrated efficacy combined with radiation, high-dose IL-2, and IL-10 through the expansion of CD8+ T cells against melanoma and renal cell carcinoma." (PMID 38398104, 2024). "In preclinical mouse studies, administration of AU-007 in combination with IL-2 induced effector T cell and NK cell proliferation in the absence of Treg expansion and showed anti-tumor efficacy in a B16F10 melanoma model." (PMID 39114660, 2024). "The use of immune-stimulating cytokines, such as interleukin-2 (IL-2) and interferon- α (IFN-α), has been approved as adjuvant treatments for melanoma." (PMID 39086722, 2024). "The PR and CR rates for patients with RCC and melanoma were 19% and 15%, respectively, for IL-2 alone and 17% and 11%, respectively, for the IL-2 and PEG-IL-2 combination." (PMID 39114660, 2024). "High-dose IL-2 treatment was the first FDA-approved immunotherapy for renal cell carcinoma and melanoma, achieving single agent complete and durable responses, albeit only in a small proportion of patients." (PMID 39114660, 2024). "In our previous study, we observed that a combination of local radiotherapy (RT), slow-release pegylated interleukin 2 (srIL-2) and antibody against cytotoxic T-lymphocyte antigen 4 (CTLA-4) induced regression of 1,000 mm3 B78 melanomas in some mice." (PMID 39076988, 2024). "Cytokine therapy for cancer, most notably IL-2 treatment, has been an FDA-approved modality in melanoma and renal cell carcinoma since 1998 and 1992, respectively." (PMID 38339310, 2024). "Specifically, high-dose IL-2 and interferon-alpha have been approved by the FDA as immunotherapy drugs for melanoma." (PMID 38835341, 2024). "NARA1 binding to IL-2 allows it to preferentially bind to dimeric IL-2R and exert effective antitumor activity by expanding CD8 + T cells in melanoma models." (PMID 39218982, 2024). "The melanoma and CRC murine models were consequently employed to test the effect of A. muciniphila and IL-2 on tumor volume and survival rate." (PMID 38585738, 2024). "The immunopotentiating effect of cisplatin was demonstrated in early trials of the combination of biochemotherapy (with IL-2 and IFN-α) for melanoma." (PMID 38280376, 2024). "For example, interleukin 2 (IL-2) is the first cytokine for NK activation in clinical practice, which has been approved by the FDA for treating metastatic kidney cancer and melanoma." (PMID 39065636, 2024). "MART-1scTCR-IL-2 is another example of a TCR-based ICK that has a similar design than 264scTCR/IL-2 but recognizes MART-1 antigen which is found on the surface of melanocytes and can be used to diagnose melanoma." (PMID 39204319, 2024). "Soon after, another cytokine, interleukin-2 (IL-2), was approved by the FDA due to its anticancer activity in RCC and melanoma." (PMID 38281269, 2024). "The intravenous administration of recombinant IL-2 was approved by the FDA for the treatment of metastatic RCC in 1992 and melanoma in 1998." (PMID 38520006, 2024).
melanoma (continued). "Numerous cytokines have been validated for use in the treatment of cancer, some of which include IL-2 for the treatment of metastatic melanoma and renal cell carcinoma, in addition to IFN as an adjuvant therapy for stage III melanoma." (PMID 38054018, 2023). "The mechanism of inhibition elicited by melanoma cells on NK cells probably consists of TGF-β release, an increase in MHC I expression, and limiting the availability of IL-2 performed by Tregs." (PMID 37895943, 2023). "In the 1990s, IL-2 (Aldesleukin) was approved by the FDA for the treatment of metastatic kidney cancer (1994) and melanoma (1998)." (PMID 36936961, 2023). "IL-15 and IL-2 can upregulate the expression of the NKG2D activating receptor on immune lymphocytes and augment NKG2D-relevant NK cells anti-tumor cytotoxicity in melanoma patients." (PMID 36936961, 2023). "Recent studies have revealed that IL7 plays a significant role in glioma, melanoma and leukemia by contributing to anti-tumor effects through the release of cytokines, including IFNG, IL1A, IL1B, TNF, IL2 and IL4." (PMID 37958451, 2023). "Patient characteristics, treatment characteristics and outcomes following the intralesional IL2 and BCG treatment for metastatic or locoregional melanoma." (PMID 37182189, 2023). "Current FDA-approved cytokine therapeutics only include IL-2 and IFN-α, which have been shown to have significant objective survival remission rates in patients with metastatic renal cancer and melanoma." (PMID 36936961, 2023). "Every-2-week dosing is under investigation in a phase 2/3, randomized controlled trial (NCT03928275), a 2-stage study of intralesional IL-2 versus combination intralesional IL-2 and BCG in stage IIIC-IVM1a melanoma." (PMID 36900196, 2023). "Together, this limited data supports the safe and effective use of intralesional IL2 and BCG for the treatment of metastatic or in-transit melanoma in this challenging patient cohort." (PMID 37182189, 2023). "We were able to generate more TILs from dogs with melanoma and were therefore able to inject both mRNA-transfected and virus-transduced CAR-TILs, as well as treatment with IL-2." (PMID 36765608, 2023). "IL-2 agonists such as IL-2/NARA1 complex, SIL2-mesenchymal stem cells (MSCs) have been demonstrated to reinvigorate TEXs in murine melanoma and colon cancer models." (PMID 37398660, 2023). "One study involved 20 patients with malignant melanoma at stages III and IV that were treated with a DC-based vaccine combined with low doses of IL-2." (PMID 36631633, 2023). "In the antigen presenting cells, (APC)/Cytokine/Chemokine/Immune category, differences in IL-2, IL-3 and STAT3 signaling pathways in melanoma and Wnt, Rho GTPases MAPK4/6 signaling pathways in HD mDC were observed." (PMID 37938561, 2023). "Interleukin 2 (IL-2), which activates T cells and NK cells, has been used in the clinic for a long time and is approved by the FDA for the treatment of melanoma." (PMID 36275738, 2022). "At least two IL-2-CD25 fusion proteins, ALKS 4230, targeting the intermediate-affinity IL-2R, and IL-2/CD25 transdimers, targeting the high-affinity IL-2R, have been described with improved antitumor efficacy in mouse B16-F10 melanoma." (PMID 35651800, 2022). "(I) Histological section of human melanoma in NSG-/- mice 7 days after treatment with patient autologous TIL and high-dose IL-2." (PMID 36124553, 2022). "Then, immunomodulators emerged to treat melanoma, including IFN and IL-2, providing a promising approach for further research." (PMID 35401191, 2022). "Thus, our results provide genetic and pharmacologic evidence indicating that DRD3 favours the production of IL-2 by CD8+ T-cells, which is associated with higher expansion and acquisition of effector function of these cells, promoting a more potent anti-tumour response in a melanoma mouse model." (PMID 36428964, 2022).